CCND1 (cyclin D1)
Diseases named in the same sentence as CCND1 in open-access papers (continued):
Sharing a sentence is not in itself a finding about the gene and the disease.
tumor (continued). "Interestingly, Bax and Bid may downregulate tumor cell invasiveness, indirectly repressing the gene expression of c-Jun, cyclin D1, β-catenin, and Sp1, which are known to stimulate invasive properties and metastasis in breast cancer." (PMID 31921862, 2019). "Therefore, a nomogram was established based on tumor grade and CCND1." (PMID 31183974, 2019). "In addition, PARP-1KO mice subjected to chemically-induced (AOM/dextran sodium sulfate) colorectal carcinogenesis were protected from tumor development compared to WT mice that carried significantly more tumors with a more aggressive phenotype characterized by upregulation of cyclin D1 and STAT3." (PMID 31877876, 2019). "However, it is notable that CCND1 was also transcribed by non‐tumor cells of the BM." (PMID 28921546, 2018). "Notably, cyclin D1 and PCNA were induced in BRCA1-deficient tumor tissues." (PMID 30652068, 2018). "Based on our sequencing data, CCND1 amplification and CDKN2A loss are common mutation signatures for NPC tumor; and we have demonstrated that PAL is an effective drug targeting cell cycle to suppress tumor growth in NPC PDX model with CCND1 and CDKN2A CNV background." (PMID 30236142, 2018). "The two drugs effectively controlled the tumor growth by blocking the β2-AR, and then consequently suppressing the expression of p-Akt, p-mTOR, Bcl-2, cyclin D1, HK2 and GLUT1, which indicated that propranolol could enhance the efficacy of vemurafenib, a member of TKIs." (PMID 29416656, 2018). "Thus, NEAT1 could regulate the BCL-2-related apoptosis pathway and cyclin D1-related pathway to promote tumor growth of OS cells." (PMID 29654165, 2018). "Therefore, many large GISTs with a small mitotic count were included in the trial, which explains the marginally significant association between absence of CCND1 expression and a small tumor diameter." (PMID 29451912, 2018). "The partners of cyclin D1 may be common to different cyclin D1-expressing tumour cells." (PMID 29066743, 2017). "Thus, it was reasonable to postulate that the NTCP down-regulation in HCC tumor tissues might be due at least in part to cyclin D1 overexpression." (PMID 28915572, 2017). "Moreover, it showed anti-tumour activity by activating NRF2 (a transcription factor traditionally deemed as a tumor suppressor) in peripheral blood mononuclear cells (PBMCs) and inhibiting NF-κB and cyclin D1 (a mediator of cell cycle progression) in tumor biopsies." (PMID 29137205, 2017). "Aberrant activation of NF-κB pathway is observed in a variety of tumor types, which regulates a range of tumorgenic processes, including proliferation, invasion, metastasis and angiogenesis, by transcriptionally activating numerous target genes, such as CCND1, MYC, MMP9 and VEGF in cancer cells." (PMID 29044221, 2017).
tumor (continued). "Therefore, expression inhibition of VEGF, Cyclin D1 and Bcl-xL could prevent angiogenesis and promote apoptosis to hinder tumor growth." (PMID 28764703, 2017). "In this study, we have demonstrated that the overexpression of MAPK7 in HCCC cells could upregulate the TGF-β expression to re-activate the miR-200b-induced inhibition of EMT and restore the expression of cyclin D1 and Cdk2 to recover cell cycle arrest for the growth of tumor cells." (PMID 29084594, 2017). "Additionally, overexpression of FHL1 dramatically inhibited the volume and the weight of tumors from HN-13 and CAL-27 xenograft models by inducing cell differentiation, decreasing expression of Ki67, Cyclin D1 and promoting apoptosis of HN-13 xenograft tumor cells." (PMID 26908444, 2016). "We showed CCND1 amplification in a SyS cell line and CCND1 rearrangement in a small percentage of cells in a subset of patient samples, although possible fusion partners and the significance of these rearrangements in a small subset of tumor cells remain elusive." (PMID 27334220, 2016). "Therefore, regulation of CCND1 at protein level can play a critical role in tumor development." (PMID 26799586, 2016). "We found that either cyclin D1 or CDK4 could not only reverse the inhibitory phenotype produced by Tspan5 but also promote the cell growth further as compared to the basal control, suggesting that cyclin D1/CDK4 have a dominant role in mediating the suppression of tumour growth by Tspan5 in GC." (PMID 27223087, 2016). "However, nothing is known, to the best of our knowledge, whether p100 can act as a tumor suppressor by attenuating Cyclin D1 protein translation." (PMID 27095572, 2016). "We investigated the immunolabeling of phosphorylated histone H3 (pHH3), cyclin D1, active caspase-3, and bcl-2 in thirteen cases each of metastatic PTC, follicular variant of PTC (FVPTC), papillary microcarcinoma (PMC) and well differentiated tumor of uncertain malignant potential (WDT-UMP)." (PMID 26863116, 2016). "Moreover, genetic deletion of β-TrCP partially increases the viability of HepG2 cells with exposure of berberine, revealing that Cyclin D1 degradation induced by berberine may contribute partially to its anti-tumor activity." (PMID 27854312, 2016). "Furthermore, the oncogenic effects of cyclin D1 is well established and inhibition of CyclinD1 inhibits not only tumor cell growth or proliferation also suppresses tumor growth in mice, indicating the significance of FOXM1/EF2K/CyclinD1 axis in TNBC cancer biology and progression." (PMID 26918606, 2016). "Finally, we analyze the correlation between cyclin D1 and miR-202 mRNA levels in 100 tumor samples and also found the negative association of miR-202 and cyclin D1 in the 100 tumor samples." (PMID 27732565, 2016). "Our results indicate that involvement of β-TrCP as E3 ligase in Cyclin D1 ubiquitination-dependent proteolysis is the mechanism in berberine′s inhibitory action on Cyclin D1 expression in HepG2 cells, and contributes partially to the anti-tumor action of berberine." (PMID 27854312, 2016). "Thus, abnormal expression of PCNA and cyclin D1 could induce a dysfunctional cell cycle and, in turn, promote angiogenesis and tumor growth." (PMID 27492854, 2016). "Thus, abnormally expressed Cyclin D1 contributes to unopposed proliferation and downstream molecular events leading to higher and prolonged Cyclin D1 mRNA and protein expression, resulting in greater tumor proliferation and shorter survival of MCL patients." (PMID 27119356, 2016). "A recent study reveals that berberine suppresses the activity of the AP-1 signaling pathway and decreases the binding of transcription factors to the Cyclin D1 AP-1 motif, indicating that transcriptional inhibition of Cyclin D1 may be involved in berberine′s anti-tumor effect." (PMID 27854312, 2016).
tumor (continued). "A previous study reveals that berberine suppresses the activity of the AP-1 signaling pathway and decreases the binding of transcription factors to the Cyclin D1 AP-1 motif, indicating that transcriptional inhibition of Cyclin D1 may be involved in the anti-tumor effect of berberine." (PMID 27854312, 2016). "In addition, we observed a reduced protein levels of WWOX and p21, an increased expression of Cyclin D1 by miR-153 overexpression, suggesting that miR-153 could also promote tumor growth in vivo." (PMID 25708809, 2015). "Moreover, RTA 405 also directly inhibits IKKβ and decreases NF-κB activity, as evidenced by reduced Ccnd1 levels in Keap1-/- MEFs The decrease in NF-κB activity may suppress tumor cell survival and promote apoptosis." (PMID 26301506, 2015). "Furthermore, phosphorylation of cyclin D1 by GSK-3β promotes its export by facilitating its association with CRM1 and the abrogation of phosphorylation results in its nuclear localization, thus promoting subcutaneous tumor formation in SCID mice." (PMID 26274615, 2015). "The finding that immune reactivity against cyclin D1 was also found in healthy donors could mean that cancer patients have a high frequency of cyclin D1-specific T cell precursors in the blood, potentially leading to a higher efficacy of cyclin D1-targeted anti-tumor vaccination." (PMID 25888530, 2015). "Indeed, STAT3-dependent tumor transformation usually correlates with enhanced expression of anti-apoptotic and pro-proliferative genes such as Bcl-2, MCL-1, cyclin-D1, and c-myc, which help preventing apoptosis and stimulating tumor growth, migration, and invasion." (PMID 26106584, 2015). "The somatic mutation profile of a tumour may contribute to this; for example, tumours harbouring or acquiring driver mutations in ESR1 or ERBB2 or amplifications at 8p12 (FGFR1) or 11q13 (CCND1) may be less responsive to targeted endocrine therapy." (PMID 25849106, 2015). "We guess that the hUCMSCs-LV-IL-21 reduced β-catenin expression and might decrease β-catenin translocation to the nucleus to decrease the expression of cyclin-D1 that may reduce the transcription of its specific target gene, resulting in inhibition of tumor cell growth." (PMID 24444073, 2014). "Additionally, MIF and cyclin D1 expression positively correlated with tumor size." (PMID 25015194, 2014). "Our pooled results are compelling evidence of a significant correlation between cyclin D1 overexpression and increased tumor size, tumor differentiation, lymphoid nodes metastasis, and advancement of clinical stage, which may adversely influence survival in OSCC." (PMID 24675814, 2014). "Therefore, decreasing cyclin D1 gene expression may be an important molecular target to control tumor proliferation." (PMID 24858012, 2014). "Thus, reducing CcnD1 expression is a clinically relevant goal and may represent an important facet of Gltn's anti-tumor activity." (PMID 24658335, 2014). "Of note, cisplatin treatment did not result in any major changes in the cellular level and localization of CDH17, β-catenin, cyclin D1 and Rb in tumor xenografts, for which cisplatin might go for different antitumor mechanism not directly impacting the Wnt pathway." (PMID 24039755, 2013). "In our study, 78% (N=21) of cyclin D1-negative tumours were associated with p16 overexpression." (PMID 23672832, 2013). "The result showed that periplocin could inhibit the cyclin-D1 expression in tumor samples." (PMID 23365613, 2013). "We already have reported that CUR induces apoptosis, causes downregulation of EGFR, Akt, cMET cyclin D1, and PCNA protein expression in CL-5 xenograft tumors, and inhibits lung cell invasion and metastasis through upregulation of HLJ1 expression in tumor cells." (PMID 23970932, 2013).
tumor (continued). "CCND1 downregulation is well characterized to decrease activation of cyclin-dependent kinases Cdk4 and Cdk6, that are not only required for G1 to S phase transition during cell cycle progression but also are major players in interaction with stromal cells that sustain tumor growth." (PMID 24143218, 2013). "Moreover, the anti-tumor effects of miR-195 in TSCC may be partially mediated by its inhibition of Cyclin D1 and Bcl-2 expression." (PMID 23451060, 2013). "Furthermore, activation of oncogenes such as Cyclin-D1 and C-myc could enhance anchorage-independent growth in mouse mammary epithelial cells on and tumor growth in severe combined immunodeficiency (SCID) mice." (PMID 22615897, 2012). "Therefore, low expression of cyclin D1 may result in hypophosphorylated pRb, the active form of this tumor suppressor." (PMID 23259795, 2012). "Therefore, it is reasonable to believe that a decrease in cyclin D1 could be potentially effective in inhibiting proliferation of tumor cells." (PMID 22949827, 2012). "Furthermore, the posttranslational regulations associated with Hu Antigen R (HuR) which connects to the enhanced translation of tumor-promoting genes, such as Cyclin D1, or the decreased translation of tumor-suppressing genes, such as caspase 2, are altered by overexpressing MCT-1." (PMID 23211466, 2012). "Similarly, the frequency of cyclin D1 immunoreactivity was higher (78.5%) in patients with moderately differentiated tumours as compared to that with the well differentiated tumours (61.2%) although the difference between the two groups was statistically not significant." (PMID 21537090, 2011). "Furthermore, these data suggest that miR-34b may suppress tumor growth through the suppression of cyclin D1 and JAG1 expression." (PMID 22113133, 2011). "In addition, both low and high CCND1 expression was associated with the shortest RFS in ID1high ER-positive tumours with no statistical significance observed in all (data not shown) or ER-negative patients." (PMID 21955753, 2011). "In this study, we showed whether the plasma C/D ratio is useful to predict tumour CCND1 amplification in preliminary 40 ESCC patients, and examined the diagnostic value of the C/D ratio to detect cancers by comparing findings in ESCC patients and healthy volunteer controls." (PMID 20389301, 2010). "Due to the low RR in this study we are unable to conclude whether tumor response was associated with a more pronounced decrease of cyclin D1 and Ki67 compared to non-responders." (PMID 21206909, 2010). "Therefore, it has been hypothesized that a decrease of cyclin D1 could be potentially effective in inhibiting proliferation of tumor cells." (PMID 21152316, 2010). "Therefore, generating cytotoxic T lymphocytes (CTLs) that kill cyclin D1-expressing tumor cells could be a promising approach." (PMID 19707583, 2009). "Additionally, PSA expression was lower in the cyclin D1-positive tumours, indicating that cyclin D1 status may affect expression of serum markers that are dependent on AR activity." (PMID 17375037, 2007). "Furthermore, other components such as EGFR and cyclin D1 could play active roles in tumour response to radiotherapy." (PMID 15956964, 2005).
tumor (continued). "Neither CCND1 amplification nor CCND1 overexpression without amplification was significantly linked to menopausal status or standard prognostic factors such as macroscopic tumour size, histopathological grade and lymph-node or progesterone receptor status." (PMID 11870541, 2002). "Thus, CCND1 overexpression could be due exclusively to the presence of oestrogen receptors, and the higher CCND1 overexpression observed in amplified tumours than in overexpressed-unamplified tumours could be due to a simple gene dosage effect." (PMID 11870541, 2002). "RSPO4 also induced significant suppression of the transcriptional activities of critical Wnt/β-catenin target genes CCND1, c-MYC and MMP7, which play important roles in tumor cell metastasis." (PMID 41522353, 2026). "Consistent with in vitro findings, xenograft tumor tissues from ARPC1B-knockdown groups exhibited significantly reduced protein levels of β-catenin, p-GSK3β, c-Myc, and cyclin D1 (p < 0.05)." (PMID 41050079, 2025). "Superior MTA1-mediated anticancer effects of Gnetin C also included a downregulation of oncogenic/tumor-promoting ETS2, pAkt/Akt, Cyclin D1, p-mTOR/pS6K/p4EBP1 and AR signaling." (PMID 40077738, 2025). "As an effect, the expression of Bcl-xL, cyclin-D1, and VEGF favors the angiogenic process and imparts survival abilities to the inner growing tumor mass." (PMID 41376623, 2025). "Grinding tumor tissues and conducting Western blot experiments demonstrated that CuB effectively reduced the protein expression levels of ZFP91, HIF-1α, c-Myc, Cyclin D1, VEGF, and MMP-9 in tumor tissues." (PMID 40860815, 2025). "A similar reduction in tumor growth was observed in HeLa cells bearing NOD-SCID mice at 25 mg/kg, with chemo sensitization and decreases in NF-κB, Cyclin D1, PCNA, and VEGF." (PMID 39861761, 2025). "Using systems pharmacology, we identified 50 anti‐HCC core targets, including EGFR, c‐Myc, ERBB2, ESR1, CCND1, and HSP90AA1, all of which play critical roles in tumor initiation, proliferation, angiogenesis, and resistance mechanisms." (PMID 40727254, 2025). "While oncogenic pathways like HER2 and cyclin D1/CDK4 have been extensively characterised in BC, the roles of tumour suppressor genes, particularly those modulating chemotherapy response, remain understudied." (PMID 40564026, 2025). "In this respect, it has been indicated that the reduction of IRSp53 expression suppresses cell-related proliferating in cells that v-Src transformed as well as tumor formation in mice, and IRSp53 knockdown suppresses p-AKT/p-Stat3/cyclin D1 signaling pathway." (PMID 41200137, 2025). "MiR-193b was demonstrated to negatively regulate tumor migration, invasion and metastasis through targeting urokinase type plasminogen activator (PLAU), dimethylaminohydrolase 1 (DDAH1), cyclin D1 (CCND1) and ETS1 in several cancer cell lines." (PMID 39972491, 2025). "CCND1 (cyclin D1) serves as a critical cell cycle regulator in NSCLC, where its overexpression drives tumor proliferation by accelerating G1/S transition and is associated with poorly differentiated histology and reduced local relapse rates." (PMID 41301482, 2025). "Cyclin D1 was shown to be overexpressed in KIT-independent GISTs, indicating its function in tumor proliferation and resistance when KIT signaling is lost." (PMID 41189865, 2025). "Functionally independently of its host RNA, 66CTG promoted the proliferation of TNBC cells and the tumor growth of TNBC xenograft by stabilizing c-Myc protein and enhancing Cyclin D1 transcription." (PMID 40628713, 2025). "Among them, seven cancer genes (ERBB2, ERBB3, PPARG, MYC, CCND1, CCNE1, MDM2) were detected to be amplified in both ctDNA and tumor tissues, indicating the reliability of ctDNA in reflecting the genomic features of tumors." (PMID 40191434, 2025).